TM6SF2 (transmembrane 6 superfamily member 2)
Diseases named in the same sentence as TM6SF2 in open-access papers (continued):
Sharing a sentence is not in itself a finding about the gene and the disease.
liver cirrhosis (9 papers, 2018 to 2022). "PNPLA3 has not only been associated with the development of liver cirrhosis and HCC, but has also shown a stronger association when compared with other risk alleles (e.g., SERPINA1, TM6SF2, MBOAT7 or GCKR)." (PMID 33804385, 2021). "There are strong genetic determinants in the development of ALD, e.g., PNPLA3, TM6SF2, and only approximately 10–20% of alcoholics develop cirrhosis of the liver." (PMID 34360999, 2021). "The individual risks for liver cirrhosis caused by NASH and alcohol are largely determined by genetic risk factors, with polymorphisms in PNPLA3 and TM6SF2 and also MBOAT7, HSD17B13 and PCKS7 being the major common genetic determinants." (PMID 34360999, 2021). "In the ALD cohort, association of liver cirrhosis remained significant also after further adjusting for risk variants of other well-established ALD genetic modifiers (PNPLA3, TM6SF2 and MBOAT7)." (PMID 34638908, 2021).
type 2 diabetes (9 papers, 2016 to 2026). "TM6SF2 is the well‐known type 2 diabetes and NAFLD risk gene." (PMID 40665476, 2025). "cT1-increasing alleles at 4 variants (in SLC30A10, SLC39A8, TM6SF2, and PNPLA3) were associated with higher ALT and AST (all with p values <2×10−5) and higher risk of type 2 diabetes (all with p <0.002, except the SLC30A10 variant)." (PMID 32247823, 2020). "This implies that NAFLD is heterogeneous and that “Obese/Metabolic NAFLD” but not NAFLD due to the PNPLA3 or TM6SF2 genetic variants predisposes to type 2 diabetes and cardiovascular disease." (PMID 27128911, 2016).
non-alcoholic steatohepatitis (8 papers, 2017 to 2025). "Common genetic variation in the patatin-like phospholipase domain containing 3 (PNPLA3) and transmembrane 6 superfamily member 2 (TM6SF2) genes have been associated with an increased risk of developing NAFLD, nonalcoholic steatohepatitis (NASH), and fibrosis in adults." (PMID 38496563, 2024). "Polymorphisms in two particular genes are more prevalent in patients with non-alcoholic steatohepatitis (NASH), patatin-like phospholipase domain-containing 3 (PNPLA3) and transmembrane 6 superfamily member 2 (TM6SF2)." (PMID 34830997, 2021).
chronic hepatitis C (6 papers, 2016 to 2022). "The impact of Transmembrane 6 superfamily member 2 (TM6SF2) E167K variant, which causes hepatocellular fat retention by altering lipoprotein secretion, on liver damage and metabolic traits in chronic hepatitis C patients is still debated." (PMID 28839198, 2017). "Genetic variants including PNPLA3-rs738409 C>G, TM6SF2-rs58542926 C>T, MBOAT7-rs641738 C>T, and HSD17B13-rs72613567 T>TA have been shown to influence progression to advanced chronic liver disease (ACLD) in patients with chronic hepatitis C (CHC)." (PMID 33917196, 2021).
liver cancer (5 papers, 2017 to 2024). An epithelial or non-epithelial malignant neoplasm that arises from the liver. "Five studies included in the current meta-analysis described the association of TM6SF2 rs58542926 T/C gene polymorphism with susceptibility to liver cancer." (PMID 31752753, 2019). "Although the relationship between TM6SF2 gene polymorphism and the risk of liver cancer has attracted attention from many researchers, results vary from study to study." (PMID 31752753, 2019). "Applying the fixed-effects model to pool research data from different locations obtained at distinct times to analyze the relationship between TM6SF2 rs58542926 locus polymorphism and liver cancer." (PMID 31752753, 2019). "To further clarify the relationship between TM6SF2 rs58542926 gene polymorphism and liver cancer,we conducted this meta-analysis of published research." (PMID 31752753, 2019). "The results showed that the TM6SF2 gene polymorphism was significantly associated with susceptibility to liver cancer." (PMID 31752753, 2019). "The results showed that TM6SF2 rs58542926 gene polymorphism was significantly associated with liver cancer susceptibility." (PMID 31752753, 2019). "In summary, TM6SF2 rs58542926 gene polymorphism is significantly associated with liver cancer susceptibility." (PMID 31752753, 2019). "To assess the association of TM6SF2 rs58542926 T/C gene polymorphism with liver cancer, we performed the current meta-analysis." (PMID 31752753, 2019). "Statistical analysis showed that the TM6SF2 gene polymorphism was significantly associated with liver cancer in the allele contrast, dominant, recessive and over dominant models (T vs C, OR = 1.621, 95%CI 1.379–1.905; CT + TT vs CC." (PMID 31752753, 2019). "Meanwhile, multiple investigators in China and abroad have carried out a large number of studies to assess the relationship between TM6SF2 rs5854292 gene polymorphism and liver cancer." (PMID 31752753, 2019). "Case-control studies assessing the relationship between TM6SF2 rs5854292 locus polymorphism and liver cancer were selected according to inclusion and exclusion criteria." (PMID 31752753, 2019). "It should be further investigated whether the TM6SF2 rs58542926 variant could be screened for early diagnosis of liver cancer." (PMID 31752753, 2019). "For example, transmembrane 6 superfamily 2 (TM6SF2) rs5854292-T variant is a risk factor for NAFLD and liver cancer." (PMID 33808094, 2021). "Mechanisms for the progression of NAFLD/NASH to liver cancer remain incompletely understood, pathogenesis could involve DNA damage of other loci, inflammatory response, genetic modifiers as PNPLA3 or TM6SF2 or mutations such as the recently reported ACVR2A mutations." (PMID 36587184, 2022).
alcoholic liver diseases (4 papers, 2018 to 2022). A disorder caused by damage to the liver parenchyma due to alcohol consumption. "There are 3 articles on the relationship between TM6SF2 gene polymorphism and HCC caused by alcoholic liver disease." (PMID 31752753, 2019).
atherosclerosis (4 papers, 2018 to 2022). A disease characterized by the build-up of fatty material and calcium deposition in the arterial wall resulting in partial or complete occlusion of the arterial lumen. "To investigate the effects of macrophage-specific Tm6sf2 deficiency on atherosclerosis, we obtained myeloid-specific Tm6sf2-deficient mice on ApoE−/− background by crossbreeding with mice expressing the LysM Cre transgene." (PMID 36139452, 2022). "In conclusion, myeloid TM6SF2 deficiency inhibits atherosclerosis development and is a potential therapeutic target for the treatment of atherogenesis." (PMID 36139452, 2022). "Our future studies will explore the functions of TM6SF2 in atherosclerosis using endothelial cell or vascular smooth muscle-specific Tm6sf2 knockout mouse models, as well as loss of function of TM6SF2 in E167K knock-in mice." (PMID 36139452, 2022). "After 12 weeks of WD challenge, male myeloid-specific Tm6sf2 deficient mice significantly slowed down the development of atherosclerosis compared to littermate control, as evidenced by the reduced plaque size in whole aortas by en face Oil Red O staining." (PMID 36139452, 2022). "The overexpression of loss-of-function TM6SF2 reduces plasma lipid levels and atherosclerosis development." (PMID 36139452, 2022). "TM6SF2-deficiency blocks this feedback and reduces inflammatory responses and foam cell formation in macrophages, presenting potential protective mechanisms underlying the alleviation of atherosclerosis in Tm6sf2 mKO mice." (PMID 36139452, 2022). "Further examination of the intracellular mechanisms underlying the regulation of TM6SF2 expression will be necessary for clarifying the function of TM6SF2 in atherosclerosis development fully." (PMID 36139452, 2022). "oxLDL, a major risk factor for the initiation and development of atherosclerosis, upregulated TM6SF2 expression in macrophages and increased TM6SF2 expression enhances oxLDL-induced inflammatory responses and foam cell formation, showing a vicious circle of positive feedback." (PMID 36139452, 2022). "Our data suggest that Tm6sf2 deficiency reduces the inflammatory responses in BMDMs and may lead to the alleviation of atherosclerosis in mice." (PMID 36139452, 2022). "We also confirmed that oxLDL upregulates the expression of ER stress markers, which can be enhanced by overexpression of TM6SF2 in macrophages, while TM6SF2 deficiency largely abolishes its effects, consistent with the protective effects during atherosclerosis development." (PMID 36139452, 2022). "This study was undertaken to illustrate the biological function of TM6SF2 in macrophages and its role during atherosclerosis development." (PMID 36139452, 2022). "Considering that inflammatory responses and lipid accumulation in macrophages are characteristic features of atherosclerotic plaques, in the current study, we sought to determine the contribution of macrophage TM6SF2 to atherosclerosis." (PMID 36139452, 2022). "Myeloid Tm6sf2 deficiency inhibited atherosclerosis and decreased foam cells in the plaques without changing the plasma lipid profile." (PMID 36139452, 2022). "In conclusion, our findings demonstrate that myeloid cell-specific Tm6sf2 deficiency inhibits atherosclerosis development in mice without affecting lipid and glucose metabolism." (PMID 36139452, 2022). "Therefore, this study determined the role of the macrophage TM6SF2 in atherosclerosis and put forward a new target for treating this disease." (PMID 36139452, 2022). "Unlike the liver-specific or systemic studies, our data demonstrate that myeloid-specific Tm6sf2 deficiency attenuates atherosclerosis development independent of circulating lipid levels." (PMID 36139452, 2022). "Our findings reveal that the suppression of macrophage TM6SF2 may become an appropriate therapeutic strategy for atherosclerosis treatment." (PMID 36139452, 2022).
atherosclerosis (continued). "Here, our data demonstrate that myeloid cell-specific Tm6sf2 deficiency inhibits atherosclerosis development independent of the circulating lipid levels." (PMID 36139452, 2022). "Whether TM6SF2 in other vascular cells, such as endothelial cells and vascular smooth muscle cells, plays a role in atherosclerosis is unknown." (PMID 36139452, 2022). "Two variants did, however, associate with differences in lipoproteins that would classically be associated with a lower risk of atherosclerosis: lower LDL-cholesterol and total TG with rs58542926 C>T near TM6SF2, and higher HDL-cholesterol with rs2642438 A>G in MTARC1." (PMID 32720691, 2020). "Therefore, the repression of TM6SF2 in macrophages could be a new therapeutic target for atherosclerosis treatment." (PMID 36139452, 2022). "These in vivo results indicate that myeloid Tm6sf2 knockout can inhibit atherosclerosis development without changing the lipid metabolism and glucose metabolism." (PMID 36139452, 2022).
alcoholic liver cirrhosis (3 papers, 2019 to 2023). A disorder of the liver characterized by the presence of fibrotic scar tissue instead of healthy liver tissue. "More recently, transmembrane 6 superfamily member 2 (TM6SF2) and membrane-bound O-acyltransferase domain-containing protein 7 (MBOAT7) gene polymorphisms have been identified as risk factors for alcoholic liver cirrhosis." (PMID 30875804, 2019). "Variants of transmembrane 6 superfamily member 2 (TM6SF2) and membrane-bound O-acyltransferase domain-containing protein 7 (MBOAT7) gene polymorphisms are identified as risk factors for alcoholic liver cirrhosis (p = 7.89 × 10−10 and p = 1.03 × 10−9, respectively)." (PMID 36077080, 2022).
viral hepatitis (3 papers, 2018 to 2026). An acute or chronic inflammation of the liver parenchyma caused by viruses. "There are two articles on the relationship between TM6SF2 gene polymorphism and HCC caused by viral hepatitis." (PMID 31752753, 2019). "Well-characterized variants such as PNPLA3, TM6SF2, HSD17B13, and MBOAT7, along with less commonly studied loci and chromosomal alterations, are discussed in relation to major etiologies, including MASLD/MASH, viral hepatitis, alcohol-related liver disease, and autoimmune conditions." (PMID 41590522, 2026).
colorectal adenoma (2 papers, 2019 to 2021). An adenoma that arises from the colon or rectum. "In addition, the transmembrane 6 superfamily member 2 (TM6SF2) gene polymorphism is associated with lean NAFLD, while it is also reported to be associated with colorectal adenoma." (PMID 34067258, 2021). "Taken together, possible factors for an association between non-obese MAFLD and colorectal adenoma include alterations in skeletal muscle mass, gut microbiota, and/or TM6SF2 gene polymorphism." (PMID 34067258, 2021).
familial hypobetalipoproteinemia (2 papers, 2016 to 2020). "APOB mutations cause familial hypobetalipoproteinemia, while TM6SF2 mutations are associated with NAFLD and progression to NASH." (PMID 32907986, 2020).
Hepatitis (2 papers, 2021 to 2023). Inflammation of the liver. "However, TM6SF2 knockdown significantly increased in lysoPC and lysoPE, both of which were recently identified as early biomarkers of NAFLD and are increased in NALFD patients with hepatitis." (PMID 34575933, 2021).
hepatitis B (2 papers, 2019). "This is in line with the human genetic association data showing that TM6SF2 E167K carriers have higher risk not only for NAFLD but also for progression of liver damage in patients infected by viral hepatitis B and C29,30." (PMID 31406127, 2019).
hyperlipidemia (2 papers, 2020 to 2026). "The genotypic and allelic frequencies of 12 SNPs in the NCAN, TM6SF2, CILP2, PBX4, SUGP1 and MAU2 were substantially different between the hyperlipidemia and normal groups." (PMID 32568739, 2020). "In conclusion, this study shows potential interactions among the NCAN, TM6SF2, CILP2, PBX4, SUGP1 and MAU2, environment and serum lipid levels in hyperlipidemia subjects." (PMID 32568739, 2020). "The incidences of the NCAN C-C (G2), TM6SF2 T-A (G3), TM6SF2 C-A (G5), CILP2 G-T (G6), PBX4-SUGP1 G-C (G8), MAU2 G-G-G-C (G9), MAU2 G-A-G-C (G10), MAU2 C-G-A-T (G12), and MAU2 C-A-G-T (G13) haplotypes were significantly different between the hyperlipidemia and normal groups (P < 0.05 for all)." (PMID 32568739, 2020).
hypertriglyceridemia (2 papers, 2022 to 2024). A laboratory test result indicating elevated triglyceride concentration in the blood. "Regarding associations with hypertriglyceridemia, SNPs on the genes of BCL7B, FADS2, and TM6SF2 were found in previous studies." (PMID 36233190, 2022).
myocardial infarction (2 papers, 2017 to 2022). Gross necrosis of the myocardium, as a result of interruption of the blood supply to the area, as in coronary thrombosis. "The function of TM6SF2 is not well characterized, but it has recently been shown that in humans this gene regulates triglyceride secretion and fat metabolism in the liver and certain variants have been associated with lowered risk of myocardial infarction." (PMID 28132643, 2017).
non-alcoholic fatty liver (2 papers, 2021 to 2022). A benign form of fatty non-alcoholic fatty liver disease where the disease has not yet progressed to the inflammation of liver. "A missense single-nucleotide polymorphism rs58542926 between the NCAN-CILP2 region and TM6SF2 gene was observed in patients with nonalcoholic fatty liver in East Asian ethnic groups and Japanese, and this missense SNP was genetically attributed to the blood lipid level in the patients." (PMID 35757483, 2022).
sarcopenia (2 papers, 2025). Progressive decline in muscle mass due to aging which results in decreased functional capacity of muscles. "It is characterized by visceral obesity, sarcopenia, and significant genetic determinants (variants of PNPLA3, TM6SF2, and MBOAT7) in normal BMI individuals." (PMID 41189623, 2025).
cocaine addiction (1 paper, 2020). "Twelve DEGs (Myct1, Gm21860, Ninj2, Fam183b, Lars2, Alkbh1, Fgf5, Frmd7, Tm6sf2, Wnt6, Batf3, and Clca1) were found to be regulated inversely among the overlap genes, which may be possible targets of RPA to disrupt the cocaine addiction process." (PMID 32489401, 2020).
overnutrition (1 paper, 2021). An imbalanced nutritional status resulting from excessive intake of nutrients. "Overnutrition and sedentary lifestyle have been considered as the main causes of NAFLD and genetic variants, including PNPLA3 rs738409, TM6SF2 rs58542926 and HSD17B13 rs72613567, in patients may accelerate or decelerate the progression of NAFLD." (PMID 33728819, 2021).
pancreatic diseases (1 paper, 2021). "So far, there is a study showing that TM6SF2 suppresses HSC activation, but there has been until now no significant study addressing the role of TM6SF2 in pancreatic diseases." (PMID 34503201, 2021).
psoriasis (1 paper, 2022). An autoimmune condition characterized by red, well-delineated plaques with silvery scales that are usually on the extensor surfaces and scalp. "In genetic analyses, PNPLA3 and TM6SF2 were both associated with increased risk of NAFLD but not with increased risk of psoriasis." (PMID 36353626, 2022). "Subsequently, we used the genetic variants PNPLA3 and TM6SF2, both strongly associated with NAFLD and high liver fat content, to test whether NAFLD was causally associated with increased risk of psoriasis." (PMID 36353626, 2022).
venous thromboembolism (1 paper, 2021). Occlusion of the lumen of a vein by a thrombus that has migrated from a distal site via the blood stream. "Among other genetic variants related to NAFLD, TM6SF2 appears to be protective, whereas MBOAT7 could favor venous thromboembolism." (PMID 34798835, 2021).
cardiovascular disease (17 papers, 2014 to 2024). "These metabolic perturbations explain the reduced plasma TG concentrations, and lower risk of cardiovascular disease associated with the TM6SF2 E167K genetic variant." (PMID 33170809, 2020). "A fundamental gap in our understanding is the impact of TM6SF2 on plasma lipid and lipoprotein metabolism in humans and its consequences for risk of cardiovascular disease." (PMID 33170809, 2020). "TM6SF2 is associated with cardiovascular disease and plays a role in oxidative stress." (PMID 34239411, 2021). "The gene symbols like HABP2, PLG, PNPLA3, and TM6SF2 exhibit specific expression in hepatic tissue, and our study also suggests their potential impact on cardiovascular disease." (PMID 38523778, 2024). "They found that the MBOAT7 T allele decreased the mortality rate of cardiovascular disease together with PNPLA3 and TM6SF2 gene variants." (PMID 37424875, 2023). "TM6SF2 rs58542926 and PNPLA3 rs738409 were both associated with reduced serum triglyceride concentrations and a lower risk of cardiovascular disease, and there was probably a synergistic interaction." (PMID 35881683, 2022). "The transmembrane 6 superfamily member 2 (TM6SF2) gene variant E167K was also associated with NAFLD, and it has a relationship with cardiovascular disease." (PMID 31213030, 2019). "In contrast, TM6SF2 regulates qualitative triglyceride enrichment and lipid synthesis, resulting in lower circulating lipoproteins such as triglyceride and LDL cholesterol and lower risk for cardiovascular disease (CVD), but with higher risk for T2DM." (PMID 39142818, 2024). "Carriers of the Glu167Lys coding variant in the TM6SF2 gene have recently been identified as being more susceptible to non-alcoholic fatty liver disease (NAFLD), yet exhibit lower levels of circulating lipids and hence are protected against cardiovascular disease." (PMID 25566323, 2014).
tumor (4 papers, 2019 to 2025). "HSD17B13, TM6SF2, PNPLA3, MTARC1, and HLA-DP1 exhibited lower expression in HCC compared with non-tumor liver tissues." (PMID 40823170, 2025).
liver (2 papers, 2019 to 2020). "In subsequent studies, the transmembrane 6 superfamily member 2, TM6SF2 (rs58542926), followed suit and was identified in an exome-wide association study of fatty liver and serum aminotransferases." (PMID 32685690, 2020).
kidney disease (1 paper, 2025). "Additionally, genetic variants such as PNPLA3, TM6SF2, and MBOAT7 were identified as contributing to both liver and kidney disease, increasing cardiometabolic risk." (PMID 40217935, 2025).